IL2 (interleukin 2)
Diseases named in the same sentence as IL2 in open-access papers (continued):
Sharing a sentence is not in itself a finding about the gene and the disease.
selenium deficiency (2 papers, 2021 to 2025). A nutritional deficiency disease resulting from inadequate selenium levels in the body, which can lead to impaired function of selenoproteins essential for antioxidant defense and thyroid hormone metabolism. "Selenium deficiency is associated with reduced lymphocyte blastogenesis, impaired IL-2 synthesis, and weaker T-cell signalling." (PMID 41375420, 2025). "Selenium deficiency can shift TH1/TH2 balance toward higher level of Th2 phenotype (IL4 cytokine), while this balance can shift toward TH1 phenotype (IL2, INF-γ cytokine production) in cases with selenium supranutrition." (PMID 35005019, 2021).
Shock (2 papers, 2019 to 2025). The state in which profound and widespread reduction of effective tissue perfusion leads first to reversible, and then if prolonged, to irreversible cellular injury. "We observed that the percentage of IL-2–producing cells was significantly decreased among CD4+ T cells at D1 and D3 and among CD8+ T cells at D1 in patients with septic shock in comparison with HVs." (PMID 30995946, 2019).
sialadenitis (2 papers, 2021 to 2023). Sialadenitis is an infection of the salivary glands. "Here, we revealed that exogenous VIP upregulated the levels of IL‐2 and IL‐10, as well as alleviated sialadenitis with dry mouth." (PMID 37506142, 2023). "Moreover, RORγ-transgenic mice, an established SS-like sialadenitis mice model, were reported to induce the expression of IL-2-mediated CD25 and CD69 on CD4+ T cells." (PMID 33726818, 2021).
skin infection (2 papers, 2018 to 2023). An inflammatory process affecting the skin, caused by bacteria, viruses, parasites, or fungi. "Levels of the proinflammatory cytokines IL-1, IL-6, and TNF-α were elevated during wound healing, consistent with previously reported results showing elevated IL-1, IL-6, IL-10, TNF-α, IL-2, IL-8, IL-13 and granulocyte colony-stimulating factor (G-CSF) in the skin infection wound model." (PMID 36901790, 2023).
sporotrichosis (2 papers, 2019 to 2025). The commonest and least serious of the deep mycoses, characterized by nodular lesions of the cutaneous and subcutaneous tissues. "This study unveils the dual role of IL-18 in human sporotrichosis caused by S. globosa—amplifying both Th1 and Th2 responses but ultimately driving pathogenic Th2 polarization through IL-2 crosstalk." (PMID 40489556, 2025). "We further investigated local expression of IL-2 in sporotrichosis lesions via IHC." (PMID 40489556, 2025). "Immunization with rSsEno plus PGA induced a predominantly T-helper 1 cytokine pattern after in vitro stimulation of splenic cells with rSsEno: elevated levels of IFN-γ and IL-2, as well as of other cytokines involved in host defense against sporotrichosis, such as TNF-alpha, IL-6, and IL-4." (PMID 31748544, 2019).
squamous intraepithelial lesion (2 papers, 2012 to 2014). "The mother of the child ID6B, who had the highest levels of IFN-γ, TNF-α and IL-2, had cervical disease during the entire FU, in which the disease varied from non-squamous intraepithelial lesion (NSIL) to CIN3 with five different HPV genotypes identified." (PMID 24524328, 2014).
steatosis (2 papers, 2022 to 2023). Increased lipid within the cytoplasm of cells. "For instance, compared to Zeb1WT/ApoeKO mice, Zeb1∆M/ApoeKO mice had higher body weight, greater steatosis, higher WAT immune infiltration, higher serum levels of pro-inflammatory markers (IL1β, IL2, IL12, leptin, CCL2), higher cholesterol and LDL, and lower HDL and glucose tolerance." (PMID 38097578, 2023).
Streptococcus pneumonia infection (2 papers, 2024). "An animal experiment indicated that Streptococcus pneumonia infection incurs pulmonary inflammation and IL-2 elevation in the lungs." (PMID 38967887, 2024).
Supraventricular tachycardia (2 papers, 2018 to 2021). Supraventricular tachycardia (SVT) is an abnormally increased heart rate (over 100 beats per minute at rest) with origin above the level of the ventricles. "Levels of IL-2 have been associated with reduced incidence of postoperative AF and supraventricular tachycardia." (PMID 35083300, 2021).
T cell deficiency (2 papers, 2016 to 2021). "The low levels of IL-2 in serum are explained by the well-known T-cell deficiency of A-T patients." (PMID 32815118, 2021).
TAFRO syndrome (2 papers, 2018 to 2024). "Considering the mechanism of action of CsA, IL-2 may play a pivotal role in TAFRO syndrome in addition to IL-6." (PMID 34171004, 2018).
tick-borne encephalitis (2 papers, 2017 to 2020). Tick-borne encephalitis is caused by an arbovirus of the Flaviviridae family (tick-borne encephalitis virus, TBEV), transmitted principally by the bite of the Ixodes ricinus tick. "Tick-borne encephalitis–specific IL-2 concentrations were significantly increased in the obese group before booster compared to controls and remained so 1 week after booster with only marginal changes; also, mitogenic stimulation with SEB resulted in higher IL-2 levels in the obese group." (PMID 32528467, 2020).
Tourette’s disorder (2 papers, 2021 to 2025). "Abnormal cytokines, such as monocyte chemotactic factor-1 (MCP-1), interleukin-2 (IL-2), and protein tyrosine phosphatase receptor-N (PTPR-N) were noted in patients with Tourette’s disorder." (PMID 40103604, 2025).
tularemia (2 papers, 2020 to 2023). Tularemia is an infection caused by the bacterium Francisella tularensis. "Serum levels of eotaxin, G-CSF, IFNα, IFNγ, IL-1β, IL-2, IL-6, IL-8, IL-10, IP-10, MCP-1, MIP-1α, MIP-1β, and PDGF were significantly increased in tularemia patients when compared to healthy controls and/or between different time points of sampling." (PMID 33114188, 2020). "Specifically, IL-2, MIP-1β, TNF, and IL-7 all fulfilled the criterion and the former three of these cytokines have previously been observed to correlate the control of infection in a human co-culture model and also in an animal models of tularemia." (PMID 37781364, 2023).
urticaria (2 papers, 2019 to 2023). A vascular reaction of the skin characterized by erythema and wheal formation due to localized increase of vascular permeability. "In patients with urticaria, there is an observed increase in IL-10 production and a decrease in IL-2 levels, consistent with the findings of the present study." (PMID 37954607, 2023). "95% CI = 1.020-1.184, p = 1.26e-02), and IL-2 on urticaria (OR = 0.712, 95% CI = 0.531-0.955, p = 2.33e-02)." (PMID 37954607, 2023). "The association of LP with IL-4 (OR = 1.099, 95% CI = 1.020-1.184, p = 1.26e-02) and urticaria with IL-2 (OR = 0.712, 95% CI = 0.531-0.955, p = 2.33e-02) remained significant at the Bonferroni-corrected significance threshold (p = 0.05/2 = 0.025)." (PMID 37954607, 2023). "Urticaria is mediated by mixed T helper (Th) 1/Th2-reactive lymphocytes, with Th1 cells primarily secreting IL-2 and Th2 cells secreting IL-10." (PMID 37954607, 2023). "On the other hand, when immune skin diseases served as the exposure variable, LP affected eotaxin, IL-12p70, IL-4, IL-16, and MCP-1 and urticaria affected IL-2 and MCP-1." (PMID 37954607, 2023).
varicella (2 papers, 2018 to 2024). "Specifically in the case of varicella, IL-2 has been detected in the serum of varicella patients and it has been demonstrated that VZV-specific T cells produce IL-2 upon stimulation with VZV lysate." (PMID 29709039, 2018).
venous thromboembolism (2 papers, 2019 to 2023). Occlusion of the lumen of a vein by a thrombus that has migrated from a distal site via the blood stream. "While IL-2 administration can have toxic effects — including venous thromboembolism, capillary leak, and activation of effector T cell responses due to the expression of variable-affinity IL-2 receptors on endothelial, T, and NK cells — low-dose IL-2 administration was well tolerated in that trial." (PMID 37463441, 2023). "Standard-dose intravenous recombinant interleukin-2 (rIL-2) is indicated for the treatment of some subtypes of cancer; however, severe adverse events, including venous thromboembolism (VTE), may complicate its administration." (PMID 31073219, 2019).
viral warts (2 papers, 2018 to 2021). "Cimetidine activates Th1 cells to produce interleukin (IL)-2, IL-12, tumor necrosis factor (TNF)-α, and interferon (IFN)-γ and their expression correlates with improvement in cellular immunity and wart remission." (PMID 29642499, 2018). "The expression levels of IFN-γ and IL-2 mRNA were correlated with wart remission, as evidenced by real-time PCR of select punch biopsy specimens, and IL-2 or IFN-γ mRNA levels were significantly increased in tissues of effectively treated viral warts." (PMID 33531926, 2021).
Wilms tumor (2 papers, 2022). An embryonal neoplasm characterized by the presence of epithelial, mesenchymal, and blastema components. "IL-2 combined with IL-15 enhanced the expression of NKG2D receptor to inhibit Wilms’ tumor via the mitogen-activated protein kinase (MAPK) signaling pathway." (PMID 36601109, 2022). "To evaluate the tumor toxic effects of uncultured and cytokine (IL-2 and IL-15) coculture NK cells, we have chosen two types of tumor cell lines including human Wilms' tumor (G401 and SK-NEP-1) and as the targets in antitumor assay." (PMID 36213822, 2022).
Wilson disease (2 papers, 2024). A very rare inherited multisystemic disease presenting non-specific neurological, hepatic, psychiatric or osseo-muscular manifestations due to excessive copper deposition in the body. "Compared with controls, in patients with Wilson disease, there was a significant increase in plasma of T helper (Th) 1 cells (IL-2, TNF-α, and TNF-β), Th2 cells (IL-5, IL-10, and IL-13), and Th17 (IL-23) (p < 0.05)." (PMID 38928368, 2024). "Compared with controls, in patients with Wilson disease, there was a significant increase of plasma of T helper (Th) 1 cells (IL-2, TNF-α, and TNF-β), Th2 cells (IL-5, IL-10, and IL-13), and Th17 (IL-23) (p < 0.05)." (PMID 38731973, 2024).
-deficient (1 paper, 2014). "In GH-deficient (GHD) patients, who exhibit major reductions in serum IGF-1, there is significantly impairment of natural killer (NK) cell activity, both unstimulated and stimulated by INFγ or IL-2." (PMID 24341939, 2014).
actinopathies (1 paper, 2025). "Rescue of T-cell activation by the addition of exogenous IL-2 in actinopathies was previously reported by our group and others in CARMIL2 deficiency and WAS protein knockout mouse model." (PMID 40748410, 2025). "Targeted therapeutic approaches, such as IL-2 and dupilumab, warrant further investigation and may have broader applications in other actinopathies." (PMID 40748410, 2025).
acute liver failure (1 paper, 2006). Rapid deterioration of liver function causing encephalopathy and coagulopathy. "Elevated serum levels of several cytokines, including TNF-α, sTNF-αR1, sTNF-αR2, IL-2, IL-2R, IL-4, IL-6, IL-8, IL-10, and interferon-γ, have been described in patients with ACLF, whereas other studies reported normal TNF-α levels in patients with ACLF or acute liver failure." (PMID 17156425, 2006).
adrenocortical tumor (1 paper, 2015). "Interestingly, Willenberg and colleagues provided evidence of the involvement of immune cells and interleukin-2 (IL-2) cytokine stimulation in the formation of an adrenocortical tumor in a patient with Cushing’s syndrome." (PMID 25767716, 2015).
adult onset asthma (1 paper, 2024). "In turn, current smoking status was causally associated with IL-2-sRβ plasma levels (MR β = −0.18, 95% CI −0.26 to −0.10; tier 2 finding), suggesting a possible biological mechanism for the effect of smoking cessation on reducing adult-onset asthma risk (causal OR 1.55, 95% CI 1.16 to 2.07)." (PMID 39327534, 2024).
allergic conjunctivitis (1 paper, 2011). "A study reported increases in IL-1β, IL-2, IL-5, IL-6, IL-12, IL-13, in seasonal allergic conjunctivitis (SAC), vernal keratoconjunctivitis (VKC) and atopic keratoconjunctivitis (AKC), while IL-4, IFN-γ and IL-10 levels were increased in SAC and VKC compared to controls." (PMID 21298010, 2011).
allergic contact dermatitis (1 paper, 2016). An inflammatory skin condition caused by an immune response to direct contact between the skin and an allergen. "Also a statistically significant increase in IL-2 was evidenced, in agreement with previous reports that indicate IL-2 as an early occurring type-1cytokine in patients with Ni allergic contact dermatitis." (PMID 27881114, 2016).
alveolitis (1 paper, 2009). "Mixed lymphocytic/neutrophilic alveolitis was characterized by increased IL-2 levels compared with ILD-negative SSc patients (P = 0.02, data not shown)." (PMID 19615053, 2009).
amebiasis (1 paper, 2018). A parasitic infectious disorder caused by amoebas. "Moreover, the significance of IL-2 in protection from amebiasis in humans or the mouse model is not known." (PMID 29900011, 2018).
amoebic colitis (1 paper, 2011). "On the other hand, in experimental amoebic colitis the same intensity of parasitism and inflammation was observed in animals deficient in IL-2, IFN-gamma, and NO." (PMID 21356065, 2011).
anal melanoma (1 paper, 2024). A melanoma arising from the anus. "Interferon, interleukin-2 (IL-2), dacarbazine, paclitaxel, and temozolomide have demonstrated favorable efficacy in treating anal melanoma." (PMID 39624501, 2024). "The combination of IL-2 and ipilimumab, administered at a dosage of 3 mg/kg, demonstrated efficacy in patients with unresectable anal melanomas." (PMID 39624501, 2024).
anaphylaxis (1 paper, 2020). An acute hypersensitivity reaction that occurs from exposure to an allergen. "In order to determine if allergen-sensitization alone is sufficient to induce susceptibility to IL-2/JES6-mediated exacerbation of anaphylaxis, mice were treated with IL 2/JES6 directly after allergen sensitization but before the first oral allergen challenge." (PMID 33362780, 2020). "Using this model, we confirmed that IL-2 agonist treatment prior initial exposure to allergen, inhibits allergic sensitization and prevents allergen challenge-induced anaphylaxis." (PMID 33362780, 2020). "To determine how IL-2/JES6 increases IgE-mediated mast cell responses and exacerbates anaphylaxis, we investigated the effects of IL-2/JES6 treatment on the size of mast cell populations in the gut, early events in mast cell activation, and cytokine responses by T helper cells." (PMID 33362780, 2020). "Hence, preventive treatment with the IL-2 agonist IL-2/JES6 blocked anaphylaxis in our model, most likely by expanding Treg populations and decreasing allergen-specific IgE production, rather than by inhibiting the response to histamine." (PMID 33362780, 2020). "Therefore, we tested whether the IL-2/JES6-induced increase in IFN-γ production could be responsible for the increased mast cell response and exacerbated anaphylaxis observed in allergic mice." (PMID 33362780, 2020). "Together, these experiments demonstrate that IL-2/JES6 administration that is first administered after mice have been sensitized does not affect allergen-specific IgE, but exacerbates anaphylaxis and increases the allergen-reactivity of IgE-sensitive effector cells, most likely mast cells." (PMID 33362780, 2020). "Thus, the IL-2/JES6-induced increase in mast cell degranulation and anaphylaxis severity is at least partially independent of increased Ag-specific IgE levels." (PMID 33362780, 2020).
anorexia nervosa (1 paper, 2019). A disorder most often seen in adolescent females characterized by a refusal to maintain a minimally normal body weight, an intense fear of gaining weight, a disturbance in body image, and, in postmenarcheal females, the development of amenorrhea. "Although the Th2 pathway seems to be favored in anorexia nervosa and primary malnutrition, with increased IL-4 as well as decreased IL-2 production, pro-inflammatory cytokines appear to be upregulated in anorexia nervosa." (PMID 31717370, 2019).
anterior uveitis (1 paper, 2013). Inflammation of the iris and anterior chamber of the eye. "For this reason, further studies are needed in order to confirm the possible IL2/IL21 genetic region influence on the non-anterior uveitis genetic background." (PMID 23676143, 2013). "Our results indicate that analyzed IL2/IL21, IL2RA and IL2RB polymorphisms do not seem to play a significant role on the non-anterior uveitis genetic predisposition although further studies are needed in order to clear up the influence of these loci on the non-anterior uveitis susceptibility." (PMID 23676143, 2013).
Atrophy (1 paper, 2017). Any weakening or degeneration, especially through lack of use. "IL-2, secreted mostly by T cells in the graft, can interact with epithelial cells, leading to a decrease in type IV collagen production in these cells, thus contributing directly to tubular atrophy." (PMID 29162160, 2017).
autoimmune peripheral neuropathy (1 paper, 2022). "While intraperitoneal injection of anti-IL-2 monoclonal antibodies in NOD mice accelerates diabetes onset, it also induces the development of autoimmune peripheral neuropathy in more than 50% of the treated mice." (PMID 35572553, 2022).
beta thalassemia (1 paper, 2021). Beta-thalassemia (BT) is characterized by deficiency (Beta+) or absence (Beta0) of synthesis of the beta globin chains of hemoglobin (Hb). "Decreased IFN-gamma and IL-2 levels in subjects with elevated ferritin levels indicate, according to authors, the immunosuppressive effect of iron overload in beta-thalassemia patients." (PMID 34575839, 2021).
biliary atresia (1 paper, 2021). A rare, biliary tract disease characterized by progressive obliterative cholangiopathy of the intra- and extrahepatic bile ducts, occurring in the embryonic/ perinatal period, leading to severe and persistent neonatal jaundice and acholic stool. "It is consistent with higher IL-2, IL-4, IL-6, IL-10, TNFα, and IFN-γ in patients with biliary atresia." (PMID 34630385, 2021).
Biotin deficiency (1 paper, 2025). "Biotin deficiency may impair immune responses by reducing cytokine production, including IL-2 and IFN-γ, by T-cells." (PMID 41303672, 2025).
bladder diseases (1 paper, 2023). "When DO, IC/BPS, and DV were grouped as pathological bladder diseases, 8-isoprostane, TAC, 8-OHdG, VEGF, NGF, and PGE2 were significantly higher, though IL-2 was significantly lower than in those with HSB, and the controls." (PMID 36983336, 2023).
blepharitis (1 paper, 2015). Inflammation of the eyelids near the eyelashes. "Similarly, a IL-2 double knock-out mice inoculated with HSV-1 in the conjunctiva showed higher mortality, increased magnitude of virus replication in the eye, and more pronounced blepharitis compared to IL-2-competent mice." (PMID 26253150, 2015).
bone cancer (1 paper, 2025). A primary or metastatic malignant neoplasm affecting the bone or articular cartilage. "Moreover, therapies involving cytokines that enhance the activation and multiplication of immune cells, including interleukin-2 (IL-2) and interleukin-12 (IL-12), are currently under investigation for their potential to trigger immune responses in bone cancer." (PMID 40165969, 2025).
burning mouth syndrome (1 paper, 2006). A condition characterized by a burning or tingling sensation on the lips, tongue, or entire mouth. "Concentration of IL-2 was measured in saliva samples of 30 patients suffering from burning mouth syndrome, as well as 30 healthy subjects." (PMID 16864905, 2006).
Candidemia (1 paper, 2021). A form of invasive candidiasis where species of CANDIDA are present in the blood. "Our results show that cytokines IL-8, IFN-γ, TNF-α and IL-2 were significantly elevated in the candidemia, compared to the control healthy group." (PMID 34684298, 2021). "Th-1 cytokine IL-8, IFN-γ, TNF-α and IL-2, all of which are important pro-inflammatory cytokines and essential factors in innate immunity, were found in the present study significantly elevated in the patients with candidemia compared to normal healthy control subjects." (PMID 34684298, 2021).